OLR1 (oxidized low density lipoprotein receptor 1)
Diseases named in the same sentence as OLR1 in open-access papers (continued):
Sharing a sentence is not in itself a finding about the gene and the disease.
cancer (continued). "Many lipid-related metabolic genes, including OLR-1 that encodes lectin-like oxidized low-density lipoprotein receptor-1 (LOX-1), are overexpressed in different cancer cell lines." (PMID 35449557, 2022). "Aberrant expression of OLR1 has been reported in multiple cancers; its expression induces the release of inflammatory cytokines and is closely related to cancer development and metastasis." (PMID 34576110, 2021). "OLR1 is also overexpressed in human cancers and has been found to participate in cancer cell proliferation, apoptosis, migration and angiogenesis." (PMID 31514732, 2019). "A meta-analysis of gene expression profiles in 950 cancer cell lines revealed that OLR1 was upregulated in 20% of CRC cells." (PMID 31500382, 2019). "Depletion of OLR1 has been found to block morphological transformation, inhibit cell motility and reduce tumorigenicity in different cancer cell lines." (PMID 28146073, 2017). "As a lipid-related gene, OLR1 has been proved as a common hub between metabolism and cancer gene networks." (PMID 26061746, 2015). "This phenomenon observed in xenografts experiments indicated the importance of OLR1 in connection between cancer and metabolic disorders." (PMID 26061746, 2015). "Remarkably, OLR1 is critical in maintaining the transformation and growth states of cancer cell lines in diverse origins." (PMID 26061746, 2015). "This is indicative of OLR1 as apossible mechanism of cancer cell-endothelium interactions, as tumor cells arecharacterized by abundance of OLR1 ligand phophatidylserine on thecellular membranes." (PMID 21637860, 2011). "Second, over-expression of OLR1 in a human cancer cellline showed significant upregulation of several genes with oncogenic properties anda significant increase in cell migration." (PMID 21637860, 2011). "Moreover, OLR1 has been recognized as a potential immune modulator, influencing the interactions between cancer cells and immune cells within the TME." (PMID 39010054, 2024). "They observed significant upregulation of OLR1 in many types of cancer." (PMID 37261073, 2023). "Notably, except for DLBC and TGCT, OLR1 exhibited positive correlations with most immune checkpoint molecules in almost all cancers, with a particularly strong correlation with HAVCR2." (PMID 37629087, 2023). "Thus, OLR1 has the potential to serve as a noteworthy biomarker and an emerging therapeutic target for cancer treatment; however, additional research is required to explore its value." (PMID 37629087, 2023). "The OLR1 gene encodes the LOX-1 receptor protein, which could facilitate the progression and metastasis of several cancers." (PMID 38022584, 2023). "Notably, our correlation analysis results showed that OLR1 was positively correlated with most immune checkpoint molecules in the majority of cancer types, with a particularly strong correlation with HAVCR2." (PMID 37629087, 2023). "SPOCK1 and OLR1 were chosen for assessment by immunofluorescence based on their significant differential expression in invasive organoids, transmembrane and intracytoplasmic protein localization, and previously reported roles in cancer cell invasion." (PMID 36881486, 2023). "In addition, OLR1 has been closely correlated with clinical outcomes in a few cancer types, which was also observed in our results." (PMID 37629087, 2023). "Furthermore, consistent with our findings, previous studies have reported that OLR1 and FGF7 are associated with adverse cancer prognosis due to alterations in immune response and TME status." (PMID 38154113, 2023). "Additionally, TMB and MSI have also been found to correlate with OLR1 expression in certain cancers." (PMID 37629087, 2023). "One of the ligands of OLR1, phosphatidylserine, would take potential responsibility of adhesion between endothelium and cancer cells, which would be the part of the reason of OLR1 promoting cancer metastasis through regulating EMT." (PMID 31718700, 2019).
cancer (continued). "OLR1 was also proved to be significant in cancer cells growth and transformed state maintenance." (PMID 31718700, 2019). "It has been shown that higher concentration of oxLDL may contribute to CRC development, probably by binding to oxidized LDL receptor (OLR1) that significantly contributes to the transformation, cell motility and growth of cancer cell lines." (PMID 30429670, 2018). "The expression of OLR1 mRNA is modulated in different cancer tissues." (PMID 28146073, 2017). "This study suggests multiple potential links between OLR1 andsusceptibility to cancer." (PMID 21637860, 2011). "It was found that the expression level of OLR1 displayed strong correlations with MSI and TMB in diverse cancers." (PMID 37629087, 2023). "OLR1, a key receptor for ox-LDL, has been reported to be upregulated in multiple cancers and promotes tumorigenesis and cancer metastasis through different signaling pathways." (PMID 37988196, 2023). "Based on online literature search, we found that OLR1, GPNMB, PRRX1 and BCAT1 promote cancer migration and invasion in various types of cancer." (PMID 29851214, 2018). "Results showed that the expression levels of OLR1 and HHIP genes in NSCLC were much higher than in other cancer types, indicating that these two genes could serve as specific biomarkers in NSCLC progression." (PMID 36011391, 2022). "It has to be noted that OLR1 is not always overexpressed in every cancer type nor in all the cell lines deriving from them, but, when functionally involved, it results to be overexpressed or abnormally spliced." (PMID 33402733, 2021). "On the other hand, presentation of OLR1 on thesurface of cancer cells did not seem to be essential for adhesion to activatedendothelial cells or for transendothelial migration." (PMID 21637860, 2011). "The level ofOLR1 in endothelial cells, however, appears to be important, asaddition of neutralizing OLR1 antibody to the medium or inhibitionof OLR1 transcription significantly impaired adhesion and transendothelial migrationin non-transfected cancer cells." (PMID 21637860, 2011). "Additionally, we found that OLR1 was correlated with both TMB and MSI in specific cancer types." (PMID 37629087, 2023). "Among these biomarkers, the lectine like oxidized low density lipoprotein receptor-1 (LOX-1) has been recently reported as playing a pivotal role for ox-LDL receptor and the related downstream signaling pathways in the onset, progression, and metastasis of cancer." (PMID 33402733, 2021). "In addition, OLR1 took part in the whole technological procedure of de novo lipogenesis, on which many cancers exclusively rely regardless of nutritional availability." (PMID 26061746, 2015).
cardiovascular disease (40 papers, 2012 to 2025). "Clinical Relevance of Mutations: Specific mutations in the OLR1 gene have been associated with an increased risk of cardiovascular diseases." (PMID 38791315, 2024). "However, it is clear that the modulation of endogenous OLR1 alternative splicing can represent a potential and promising therapeutic strategy in order to reduce ox-LDL levels and atheroma plaque formation in patients with high susceptibility to cardiovascular disease." (PMID 28146073, 2017). "However, so far the contribution of elevated Olr1 transcription and LOX-1 shedding to the increase of sLOX-1 in patients with cardiovascular disease remains elusive." (PMID 33553253, 2020).
infection (35 papers, 2012 to 2025). The state of being infected such as from the introduction of a foreign agent such as serum, vaccine, antigenic substance or organism. "As a potential determinant of tissue homeostasis in pneumonic airspaces, we have found that the lectin-like oxidized low-density lipoprotein receptor 1 (LOX-1, encoded by OLR1) plays multifunctional roles during infection." (PMID 36264633, 2022). "In the liver, however, the Olr1 expression after the infection was significantly higher in aged animals than that in young ones." (PMID 34834944, 2021).
metabolic disease (16 papers, 2015 to 2024). A congenital disorder (due to inherited enzyme abnormality) or acquired (due to failure of a metabolically important organ) disorder resulting from an abnormal metabolic process. "The role of OLR1 in tumorigenesis has only recently come to light, with previous studies primarily focusing on cardiovascular and metabolic diseases." (PMID 37629087, 2023). "The results supported the hypothesis that CTEPH is a metabolic disease as the mRNA expression level of oxidized low-density lipoprotein receptor 1 showed the greatest upregulation, while the mRNA expression level of chordin-like 1 showed the greatest downregulation." (PMID 25522749, 2015).
infectious disease (4 papers, 2015 to 2025). A disorder directly resulting from the presence and activity of a microbial, viral, or parasitic agent in humans. "The importance of OLR1 in thrombosis should be considered in a wide range of infectious diseases." (PMID 34344944, 2021).
hematological disease (1 paper, 2022). "In addition, genes associated with hematological disease (e.g., PDE7A, LMAN1, F13A1, OLR1) and mitochondrial biogenesis and redox (e.g., NOS3, ALDH5A1, PRXL2A, SLC25A13, CPT2) were also significantly altered in BPD patients." (PMID 35484630, 2022).
OLR1 also shares sentences with these, for which no sentence is quoted: Hyperglycemia (11 papers); acute myocardial infarction (10); preeclampsia (8); arteriosclerosis (7); myocardial ischemia (7); Insulin resistance (6); vasculopathy (6); angina pectoris (5); carotid atherosclerosis (5); gastric cancer (5); hepatocellular carcinoma (5); ischemia (5); osteoarthritis (5); Peri-Implantitis (5); bacterial infection (4); cardiac hypertrophy (4); cerebral infarction (4); cerebrovascular disease (4); diabetic nephropathy (4); glomerulosclerosis (4); head and neck cancer (4); kidney disease (4); metastatic tumors (4); Myocardial fibrosis (4); non-small cell lung carcinoma (4); acute respiratory distress syndrome (3); Arthritis (3); Atherosclerotic lesion (3); chronic renal failure (3); fibrosis (3).
A further 119 diseases each share a sentence with OLR1 in 3 papers or fewer.